ADK (adenosine kinase)
Diseases named in the same sentence as ADK in open-access papers (continued):
Sharing a sentence is not in itself a finding about the gene and the disease.
hepatocellular carcinoma (3 papers, 1978 to 2025). A malignant tumor that arises from hepatocytes. "Hepatocellular carcinoma cells are derived from hepatocytes, which express extremely high levels of ADK." (PMID 41231272, 2025). "In contrast to MCF7 cells, AICAr does induce NRF2 expression in hepatocellular carcinoma cells via an ADK-dependent, AMPK-independent mechanism." (PMID 41231272, 2025). "Adenosine deaminase and adenosine kinase have been measured in rat liver, 12 transplantable hepatomas, regenerating, foetal and neonatal liver, adult and neonatal rat kidney and 2 transplantable kidney tumours." (PMID 207296, 1978). "In rat hepatoma cell lines growing in culture, the toxicity of adenosine correlated inversely with the ratio of adenosine deaminase activity to adenosine kinase activity." (PMID 207296, 1978). "Last but not least, the downregulation of ADK found in hepatocellular carcinoma cells suggests the diversity of ADK changes across cancers." (PMID 35721189, 2022). "Adenosine kinase activity was decreased, relative to rat liver values, in all the hepatomas; activity of this enzyme gave a negative correlation with tumour growth rate." (PMID 207296, 1978).
hypermethioninemia (3 papers, 2015 to 2023). "The ADK gene mutations are reported to have a phenotype of global developmental delay, seizures, dysmorphic face, and biochemical anomalies, such as hypermethioninemia with increased levels of AdoMet and AdoHcy, with normal homocysteine." (PMID 37878632, 2023). "Another, unusual cause of hypermethioninemia involves biallelic mutations in the gene for adenosine kinase (ADK), also associated with neurodevelopmental delay, seizures and hepatic dysfunction." (PMID 27500280, 2016). "In the differential diagnosis of hypermethioninemia also deficiencies of S-adenosylhomocysteine hydrolase, adenosine kinase and glycine N-methyltransferase need to be mentioned." (PMID 26289392, 2015). "ADK deficiency must be considered when the symptoms including cholestasis, liver dysfunction and psychomotor delay or regression are diagnosed, especially in the presence of hypermethioninemia." (PMID 27500280, 2016).
type 1 diabetes (3 papers, 2011 to 2019). "In our study, we found that the specific loss of ADK in a β‐cell causes Ins2‐Cre±Adkfl/fl mice to be more resistant to STZ treatment, a pathological model generally for type 1 diabetes." (PMID 31044530, 2019). "The fourth SNP, rs7924176, on chromosome 10q22.2 is intronic in ADK (adenosine kinase), a gene that has been studied in the context of type 1 diabetes, and is located in a broader region showing linkage with Alzheimer's disease." (PMID 21931568, 2011). "Moreover, loss of ADK in β cells increased the resistance of mice to streptozotocin (STZ) treatment, an animal model mostly mimicking type 1 diabetes." (PMID 31044530, 2019).
atherosclerosis (2 papers, 2017 to 2022). A disease characterized by the build-up of fatty material and calcium deposition in the arterial wall resulting in partial or complete occlusion of the arterial lumen. "In addition, loss of endothelial ADK in mice leads to reduced atherosclerosis and affords protection against ischemia/reperfusion injury of the cerebral cortex." (PMID 29038540, 2017). "The translational significance of this pathway is shown in a novel mouse model where selective deletion of ADK in the endothelium confers protection against the development of atherosclerosis and cerebral ischemia/reperfusion injury." (PMID 29038540, 2017). "Elevating intracellular adenosine selectively in endothelial cells by knocking out ADK had profound protective effects against atherosclerosis and I/R injury through effects on multiple cytokine and adhesion molecule pathways." (PMID 29038540, 2017). "Here the authors show that pro-inflammatory stimuli lead to endothelial inflammation by increasing adenosine kinase expression, and that its knockdown in endothelial cells inhibits atherosclerosis and cerebral ischemic injury in mice." (PMID 29038540, 2017). "For examples, under in vivo conditions, adenosine that is released from endothelial cells in the setting of ADK deficiency may activate the A2AR or A2BR on adjacent cells such as leukocytes and macrophages to alleviate the vascular inflammation in atherosclerosis and ischemic stroke." (PMID 29038540, 2017).
endometriosis (2 papers, 2020 to 2023). The growth of functional endometrial tissue in anatomic sites outside the uterine body. "Several mQTLs specifically associated with severe (rASRM stage III/IV) endometriosis including five on chromosome 10q22.2 are also associated with eQTLs for ADK, an enzyme that regulates concentrations of extracellular adenosine and intracellular adenine nucleotides." (PMID 37587191, 2023). "Expression of four of the genes (EEFSEC, GDAP1, ADK, and SKAP1) was also significantly associated with endometriosis risk when SMR analyses were conducted using the eQTL and GWAS summary statistics." (PMID 37587191, 2023). "New endometriosis target genes detected include EEFSEC (eukaryotic elongation factor, selenocysteine-TRNA specific) on chromosome 3q21.3, SRD5A3 (steroid 5 α-reductase 3) on chromosome 4q12, ADK (adenosine kinase) on chromosome 10q22.2, and HOXC cluster on chromosome 12." (PMID 37587191, 2023).
Insulin resistance (2 papers, 2021). Increased resistance towards insulin, that is, diminished effectiveness of insulin in reducing blood glucose levels. "Endothelial ADK was significantly upregulated in mice submitted to HFD; conversely, endothelial-specific ADK deficiency protected mice from HFD-induced insulin resistance and metabolic syndrome." (PMID 34489711, 2021).
ischemic stroke (2 papers, 2017 to 2023). A stroke disorder caused by obstruction of blood flow to the brain, due to thrombotic (local blood clot formation) or embolic (due to a blood clot or other material traveling from another site) event. "The overexpression of shorter, cytoplasmatic ADK in the brain resulted in spontaneous seizures and increased brain injury after ischemic stroke but the overexpression of the longer, nuclear ADK in dorsal forebrain neurons attenuated neural stem cell proliferation." (PMID 37512494, 2023). "To investigate whether diminished adhesion molecule expression in the endothelial-specific ADK knockout mice confers neuroprotection in models of ischemic stroke, we performed a focal cerebral ischemia–reperfusion (I/R) operation in ADKVEC-KO mice and ADKWT littermates." (PMID 29038540, 2017).
liver disease (2 papers, 2016 to 2022). "In contrast, adenosine kinase (ADK, spot 39) was higher abundance in Big Bone chickens at two weeks of age and its function is known to be associated with liver disease." (PMID 27760160, 2016). "Liver constitutes the highest expression levels of ADK and thus liver disease is a characteristic feature of ADK deficiency (but not mandatory)." (PMID 36589157, 2022).
non-alcoholic fatty liver disease (2 papers, 2023 to 2024). "For instance, hepatic adenosine kinase overexpression elevated DNA methylation and reduced PPARα expression, leading to increased fatty acid oxidation and inflammation in non-alcoholic fatty liver disease." (PMID 36866528, 2023). "The first line of evidence showed that ADK expression was significantly increased in liver cells, predominantly hepatocytes, in human subjects with non-alcoholic fatty liver disease (now MASLD) (including MASH) and in a mouse model with diet-induced obesity and MASLD." (PMID 39391763, 2024).
pancreatitis (2 papers, 2022 to 2025). Inflammation of the pancreas. "Utilizing XGBoost and RF, we pinpointed 10 genes closely related to pancreatic cancer, culminating in the identification of RAP1GDS1, TOP2A, ADK, POLL, CD44, and CD4 as pivotal genes linked to hypoxia in pancreatitis." (PMID 40787634, 2025). "Further investigations, including differential expression analysis and machine learning techniques, revealed six significant diagnostic markers for pancreatitis: RAP1GDS1, TOP2A, ADK, POLL, CD44, and CD4." (PMID 40787634, 2025). "In our study, we identified key hypoxia-related genes—RAP1GDS1, TOP2A, ADK, POLL, CD44, and CD4—in pancreatitis samples using methods such as WGCNA, XGBoost, and RF algorithms." (PMID 40787634, 2025). "We then conducted qRT-PCR on serum samples from five pancreatitis patients and five healthy controls to examine the expression levels of RAP1GDS1, TOP2A, ADK, POLL, CD44, and CD4." (PMID 40787634, 2025).
squamous cell carcinoma (2 papers, 2017 to 2022). A carcinoma arising from squamous epithelial cells. "Exosomes isolated from patients with EGFR mutation showed significant increased activity of pro-MMP-9 and MMP-9 compared to exosomes isolated from serum from wild-type adenocarcinoma (ADK WT), squamous cell carcinoma, or healthy donors." (PMID 35954442, 2022). "NKX2–1 expression was also significantly higher in patients with ADK than in those with squamous cell carcinoma (SCC) (P < 0.001)." (PMID 29237428, 2017). "Compared to A549 cells treated with serum-derived exosomes from ADK WT, squamous cell carcinoma, and healthy donors, A549 cells treated with exosomes from patients with an EGFR mutation showed a significant increase of vimentin and a slight decrease of E-cadherin, canonical markers of EMT." (PMID 35954442, 2022).
status epilepticus (2 papers, 2018 to 2022). Status epilepticus is defined as a continuous seizure lasting more than 30 min, or two or more seizures without full recovery of consciousness between any of them. "Inthe present study, we improved therapeutic benefit ofWJMSCs by knocking down ADK gene and producingadenosine releasing WJMSCs to suppress seizures infamilies with status epilepticus and we stored thesecells for possible future applications." (PMID 29308612, 2018).
acute pancreatitis (1 paper, 2022). An acute inflammatory process that leads to necrosis of the pancreatic parenchyma. "Using mouse models, we investigated the effects of ADK on acute pancreatitis and found that ADK inhibition attenuates the severity of AP by limiting the infiltration of neutrophils and macrophages, suppressing the production of proinflammatory molecules and preventing acinar cell necroptosis." (PMID 35281076, 2022).
alcohol (1 paper, 2023). "We hypothesized that adenosine kinase has a beneficial effect in the context of alcohol intoxication by facilitating the metabolic clearance of adenosine." (PMID 36377091, 2023).
bipolar disorder (1 paper, 2017). A disorder of the brain that causes unusual shifts in mood, energy, activity levels and the ability to carry out day-to-day tasks. "This gene list includes new excellent candidates with putative links to bipolar disorder, including ADK, GTF2I, hnRNP-A1, HTRA2, PKD1 and RERE, which have been linked to various brain-related diseases." (PMID 28915787, 2017).
brain tumors (1 paper, 2022).
cervical cancer (1 paper, 2025). A primary or metastatic malignant neoplasm involving the cervix.
giardiasis (1 paper, 2024). An infection of the small intestine caused by the flagellated protozoan giardia lamblia. "Ara-A, which is an even worse substrate of dCK and dGK and is mainly phosphorylated by adenosine kinase in mammalian cells, could perhaps be the most interesting option of the two drugs against giardiasis." (PMID 39607702, 2024).
Glucose intolerance (1 paper, 2025). Glucose intolerance (GI) can be defined as dysglycemia that comprises both prediabetes and diabetes. "Overexpression of ADK impairs pancreatic functionality by promoting glucose intolerance, reducing β-cell mass and fasting insulin plasma levels, while β-cells proliferation downregulates ADK." (PMID 40725425, 2025).
hyperinsulinemic hypoglycemia (1 paper, 2023). An inherited autosomal recessive syndrome characterized by the disorganized formation of new islets in the pancreas and congenital hyperinsulinism. "Hyperinsulinemic hypoglycemia may also be a presenting sign in other inherited metabolic diseases that may manifest with a complex syndromic phenotype, such as adenosine kinase deficiency (OMIM #614300)." (PMID 37065762, 2023).
Intellectual disability (1 paper, 2021). "A developmental role of ADK-L is also supported by developmental defects associated with inborn human ADK deficiency, which leads to growth defects, intellectual disability, and hepatic encephalopathy." (PMID 33863781, 2021).
liver cirrhosis (1 paper, 2022). "Based on our case report, we would like to highlight that ADK deficiency should be added to the list of genes involved in cholestatic liver disorders and liver cirrhosis." (PMID 36589157, 2022).
liver failure (1 paper, 2011). A liver disease characterized by the liver losing or has lost all of its function. "Studies with the AdK knockout mouse, which causes liver failure and early postnatal death, indicate that the effects of AdK deficiency on transmethylation reactions are the main underlying causes for its lethal effect." (PMID 21586167, 2011).
mitochondrial DNA depletion syndrome (1 paper, 2016). The mitochondrial DNA (mtDNA) depletion syndrome (MDS) is a clinically heterogeneous group of mitochondrial disorders characterized by a reduction of the mtDNA copy number in affected tissues without mutations or rearrangements in the mtDNA. "SAHH deficiency, mitochondrial DNA depletion syndrome and ADK deficiency were the main differential diagnoses in this case." (PMID 27500280, 2016).
myocardial infarct (1 paper, 2021). "The ADK inhibitor ABT702 significantly reduced myocardial infarct size compared with that of the I/R group." (PMID 33523568, 2021). "In the current study, ADK inhibition limited myocardial infarct size and improved cardiac function after I/R injury by preventing programmed cell death; both apoptosis and necroptosis were regulated by XIAP." (PMID 33523568, 2021). "Compared with the blank vector group, knockdown of ADK significantly limited the enlargement of myocardial infarct size after I/R injury." (PMID 33523568, 2021).
myocardial ischemia (1 paper, 2024). A disorder of cardiac function caused by insufficient blood flow to the muscle tissue of the heart. "For instance, cardiomyocyte ADK deletion was reported ameliorating myocardial ischemia/reperfusion injury and ADK inhibition achieve sustained cardioprotection." (PMID 39369254, 2024).
non-small cell lung carcinoma (1 paper, 2015). A group of at least three distinct histological types of lung cancer, including non-small cell squamous cell carcinoma, adenocarcinoma, and large cell carcinoma. "Notably, we found that the two tumorigenic clones C1 and C5 represented SCC and ADK, respectively, the major subtypes of non-small cell lung carcinoma." (PMID 26244663, 2015).
ovarian carcinoma (1 paper, 2025). A malignant neoplasm originating from the surface ovarian epithelium. "For example, ADK::KAT6B fusion (NSCLC P13756) was observed in a woman with ovarian cancer." (PMID 40661875, 2025).
Parkinson disease (1 paper, 2025). A progressive degenerative disorder of the central nervous system characterized by loss of dopamine producing neurons in the substantia nigra and the presence of Lewy bodies in the substantia nigra and locus coeruleus. "Astrogliosis, via overexpression of adenosine kinase, induces a deficiency in the homeostatic tone of adenosine, which is a common hallmark of epilepsy, AD, Parkinson's disease (PD), and amyotrophic lateral sclerosis." (PMID 40255917, 2025).
Seizure (1 paper, 2022). A seizure is an intermittent abnormality of nervous system physiology characterized by a transient occurrence of signs and/or symptoms due to abnormal excessive or synchronous neuronal activity in the brain. "Seizure-induced adenosine surges can result in changes in ADK, which together with adaptive alterations of the density and activity of adenosine receptors maintain balanced adenosine activities in epileptic sites." (PMID 35754505, 2022).
Sepsis (1 paper, 2008). Sepsis is defined as life-threatening organ dysfunction caused by a dysregulated host response to infection. "Inhibition of rephosphorylation of adenosine by adenosine kinase inhibitors or its degradation by adenosine deaminase (ADA) improves survival of sepsis in various sepsis models." (PMID 18847498, 2008).
sleeping sickness (1 paper, 2009). "The cytotoxic hyperactivation of adenosine kinase does not only provide an opportunity for the chemotherapy of sleeping sickness, but when explored against other pathogens or tumor cells, hyperactivation of metabolic key enzymes may well find further pharmacological applications." (PMID 19707572, 2009).
sudden infant death syndrome (1 paper, 2021). Unexpected death in infancy which remains unexplained following autopsy, review of the medical history, and investigation of the death circumstances and death scene. "(iii) SUDEP may share a similar etiology with sudden infant death syndrome (SIDS), a condition that has been linked to global ADK deficiency in neonates." (PMID 34144123, 2021).
venous thromboembolic disease (1 paper, 2022). "For example, the Pitta Kapha replicated profile GWAS SNPs in RASA2, ADK and CTU1 have an association with immuno-metabolic traits and diseases, blood and coagulation related traits/diseases such as venous thromboembolic disease." (PMID 35330488, 2022).